RETN (resistin)
Diseases named in the same sentence as RETN in open-access papers (continued):
Sharing a sentence is not in itself a finding about the gene and the disease.
Sciatica (2 papers, 2021). Pain in the lower back and hip radiating in the distribution of the sciatic nerve. "Combining these studies, a potential link between TLR4, MMP9, MPO, CAMP, RETN, and sciatica can be established, but microarray analysis showed that the expression of these genes was not changed after integrated TCM treatment." (PMID 33573686, 2021). "The PPI network suggested that TLR4, MMP9, MPO, CAMP, RETN, TLR5, and IL1RN were key genes in the dysregulation of genes in the peripheral blood of patients with sciatica." (PMID 33573686, 2021). "Consistent with the microarray data, the expression levels of the key genes (TLR4, MMP9, MPO, CAMP, RETN and TLR5) were significantly increased in patients with sciatica compared with healthy controls." (PMID 33535986, 2021). "Network analysis identified TLR4, MMP9, MPO, CAMP, RETN and TLR5 as key genes contributing to the dysregulation of genes in the peripheral blood of patients with sciatica." (PMID 33535986, 2021). "Bioinformatic analysis revealed that most of the DEGs-baseline were related to immunity and the inflammatory response and that TLR4, MMP9, MPO, CAMP, RETN, TLR5, and IL1RN were key genes involved in the dysregulation of genes in the peripheral blood of patients with sciatica." (PMID 33573686, 2021).
scoliosis (2 papers, 2022 to 2024). A congenital or acquired spinal deformity characterized by lateral curvature of the spine. "We found a significant association between RETN and the progression of scoliosis, highlighting its potential role in the disease's pathophysiology." (PMID 39664590, 2024). "The results demonstrate a significant association between the cytokine Resistin (RETN) and scoliosis progression, suggesting RETN as a potential therapeutic target." (PMID 39664590, 2024). "This study provides evidence of a significant causal relationship between RETN and scoliosis, emphasizing its potential as a therapeutic target." (PMID 39664590, 2024). "The findings highlight the critical role of RETN in scoliosis progression and underscore the complex interplay of genetic and inflammatory pathways." (PMID 39664590, 2024). "Particularly considering RETN's role in modulating inflammation and immune responses, understanding its expression and activity in patients with scoliosis could be crucial for disease management." (PMID 39664590, 2024). "Nevertheless, the specific role of RETN in the pathology of scoliosis remains unclear, necessitating further research to explore this." (PMID 39664590, 2024). "Future studies that reveal the potential connection between RETN and the progression of scoliosis could provide new insights into the complex pathophysiology of the condition and may guide the development of new therapeutic strategies." (PMID 39664590, 2024). "Future therapies could focus on modulating RETN‐related pathways to mitigate inflammation and slow or prevent disease progression, offering new hope for improved scoliosis treatment strategies." (PMID 39664590, 2024). "Importantly, the identification of RETN as a key player in scoliosis progression opens new avenues for potential clinical interventions." (PMID 39664590, 2024). "Investigating the role of the TLR4/NF‐κB pathway in scoliosis could provide new insights into how resistin influences inflammation‐driven disease progression." (PMID 39664590, 2024). "Animal models should be used to further investigate these pathways, focusing on how modulating resistin‐related signaling could slow or prevent scoliosis progression." (PMID 39664590, 2024). "Disruption of this pathway by resistin has been linked to metabolic disorders, and exploring how resistin‐mediated AMPK dysregulation might affect scoliosis progression could open new avenues for research, particularly in understanding the link between metabolic dysfunction and spinal deformities." (PMID 39664590, 2024). "Future studies could explore how resistin modulates ECM production and degradation, contributing to the structural changes observed in scoliosis." (PMID 39664590, 2024). "While no specific RETN‐targeted therapies have been developed for scoliosis, its involvement in modulating immune responses and systemic inflammation makes it a promising candidate for future therapeutic strategies." (PMID 39664590, 2024). "Moreover, resistin's influence on adipogenesis and extracellular matrix (ECM) remodeling through pathways such as the TGF‐β/SMAD signaling cascade may also play a significant role in scoliosis development." (PMID 39664590, 2024).
thyroid disease (2 papers, 2022 to 2023). "T2DM patients with clinical thyroid dysfunctions showed higher levels of circulating resistin, visfatin, chemerin and inflammatory factors, compared with the T2DM group and T2DM coexisted with subclinical thyroid diseases." (PMID 36830883, 2023).
ulcerative colitis (2 papers, 2011 to 2021). An inflammatory bowel disease involving the mucosal surface of the large intestine and rectum. "Moreover, studies have suggested that adipokines secreted by adipose tissue (TNFα, IL-1, IL-6, leptin, resistin and adiponectin) are closely associated with inflammatory bowel diseases such as ulcerative colitis." (PMID 22073943, 2011).
acute GVHD (1 paper, 2016). "However, resistin values were significantly lower in patients with acute GVHD grades 2-4 than in autologous controls (4.6 vs 7.3 ng/mL, P = 0.030)." (PMID 27374827, 2016).
acute leukemia (1 paper, 2006). A clonal (malignant) hematopoietic disorder with an acute onset, affecting the bone marrow and the peripheral blood. "In contrast to these discrepant results, various investigations in man consistently revealed the presence of resistin in myeloid cells: both primary monocyte-derived and/or differentiated macrophages as well as in primary acute leukemia cells and the myelocytic lines U937 and HL60." (PMID 17183659, 2006).
airways allergies (1 paper, 2023). "Previous studies have reported a conflicting role of serum resistin levels in mouse-models of airways allergies." (PMID 38139075, 2023).
alopecia areata (1 paper, 2021). Loss of scalp and body hair involving microscopically inflammatory patchy areas. "Further studies are needed to evaluate the role of resistin in patients with alopecia areata and its decreased level irregardless of severity or activity of the disease." (PMID 34226603, 2021). "Patients with alopecia areata are characterized by an abnormal serum level of adipokines, particularly adiponectin and resistin." (PMID 34226603, 2021). "In present study the level of resistin observed in patients with alopecia areata was decreased compared to healthy controls." (PMID 34226603, 2021). "The aim of the study was to evaluate the serum level of adiponectin, resistin and leptin in patients with alopecia areata in comparison to healthy controls." (PMID 34226603, 2021). "In patients with alopecia areata the lower serum level of resistin, which is considered as a molecule aggravating inflammation, may be explained by its local pro-inflammatory action being independent from the systemic concentration." (PMID 34226603, 2021). "To date, the role of resistin has not been confirmed in alopecia areata." (PMID 34226603, 2021).
Anorexia (1 paper, 2014). Lack of desire to eat (loss of appetite). "In addition, resistin was negatively correlated with BMI, anorexia-associated parameter." (PMID 25049439, 2014).
antisynthetase syndrome (1 paper, 2022). Antisynthetase (AS) syndrome is a clinically heterogeneous form of idiopathic inflammatory myopathy characterized by myositis, arthralgia, Raynaud phenomenon, mechanic hands, interstitial lung disease (ILD), and serum autoantibodies to aminoacyl transfer RNA synthetases (anti-ARS). "Another study showed that serum resistin levels were increased in patients with antisynthetase syndrome." (PMID 35592858, 2022).
aortic aneurysm (1 paper, 2024). A ruptured aneurysm located in the wall of the proximal portion of the descending aorta proceeding from the arch of the aorta. "Interestingly, we found cells expressing both CB1R and resistin in the CD68-positive area of the atheromatous plaque of aortas obtained from patients with aortic aneurysm." (PMID 39050819, 2024).
Apnea (1 paper, 2023). Lack of breathing with no movement of the respiratory muscles and no exchange of air in the lungs. "Among the adipokines studied, leptin emerges as being most closely related to the severity of apnea, while the levels of IL-6, ET-1, and resistin are elevated during AMI regardless of OSA’s presence." (PMID 37834123, 2023).
asthenia (1 paper, 2022). Clinical sign or symptom manifested as debility, or lack or loss of strength and energy. "Moreover, we found that lymphocytes and ALT levels correlate positively with the presence of asthenia or fatigue at 4–6 weeks; meanwhile CRP, troponin, resistin, IL-8 and MCP-1 levels correlate negatively (data not shown)." (PMID 35330391, 2022).
atopic asthma (1 paper, 2018). An asthma that is characterized by symptoms that are triggered by an allergic reaction caused by inhaled allergens such as dust mite allergen, pet dander, pollen and mold. "Positive association was reported in study from South Korea that indicated lower resistin levels in patients with atopic asthma compared to control groups." (PMID 29584687, 2018).
autism (1 paper, 2019). Persistent deficits in social interaction and communication and interaction as well as a markedly restricted repertoire of activity and interest as well as repetitive patterns of behavior. "Leptin, adiponectin and resistin are the only three molecules that belong exclusively to the class of adipokines and they have been studied in a limited number of researches concerning autism." (PMID 31835709, 2019).
bacterial pneumonia (1 paper, 2020). Acute infection of the lung parenchyma caused by bacteria (e.g., Streptococcus pneumoniae, Haemophilus influenzae, Chlamydia pneumoniae, Mycoplasma pneumoniae, and Legionella pneumophila). "Moreover, the level of pulmonary resistin, in the acute bacterial pneumonia, was significantly decreased in the DIO mice, not in the lean mice." (PMID 32685099, 2020).
bacterial sepsis (1 paper, 2025). "Resistin expression was notably higher in patients with G- bacterial sepsis contrasted with G+ bacterial sepsis (P < 0.05) Furthermore, resistin levels were significantly correlated with PCT, IL-6, and PDL1 (P < 0.05)." (PMID 40568710, 2025). "However, this study found that resistin expression levels were substantially raised in patients with Gram-negative sepsis, suggesting its potential use in identifying G-/G+ bacterial sepsis." (PMID 40568710, 2025).
Behçet disease (1 paper, 2019). "The expression of resistin was found to be upregulated in AN and Behçet disease, but further studies are still needed to reveal the underlying mechanisms." (PMID 31824416, 2019).
bipolar depression (1 paper, 2023). "In the case of resistin, the main correlation observed was that the baseline concentration of this proinflammatory adipokine was significantly lower in patients with unipolar versus bipolar depression." (PMID 37891727, 2023).
bleeding (1 paper, 2015). "Increased resistin concentration has been detected after the head trauma or intracerebral bleeding and it has been suggested that its concentration is proportional with the magnitude of injury." (PMID 26112052, 2015).
brain injury (1 paper, 2010). Acute and chronic (see also brain INJURIES, CHRONIC) injuries to the brain, including the cerebral hemispheres, CEREBELLUM, and brain STEM. "• In patients with traumatic brain injury, plasma resistin level increased during the 6-hour period immediately, peaked within 24 hours, plateaued at day 2, decreased gradually thereafter and was substantially higher than that in healthy controls during the 7-day period." (PMID 21029428, 2010).
breast cyst (1 paper, 2016). A fluid-filled closed cavity or sac that is lined by an EPITHELIUM and found in the BREAST. "So far there is the lack of experimental and clinical studies assessing the impact of leptin, adiponectin, and resistin on the risk of cancer development in women with breast cysts." (PMID 27293305, 2016). "The breast cyst fluid levels of leptin, adiponectin, and resistin were significantly decreased compared to plasma in both study groups." (PMID 27293305, 2016). "Similar observations concern plasma and breast cyst fluid levels of adiponectin and resistin." (PMID 27293305, 2016). "Contrary to leptin, resistin, and adiponectin, IL-6 levels were similar and the levels of visfatin/NAMPT and TNF-α in breast cyst fluid were significantly greater than in the circulation in both study subgroups." (PMID 27293305, 2016). "The levels of leptin, adiponectin, and resistin were significantly lower in breast cyst fluid than in plasma regardless of the cyst type." (PMID 27293305, 2016).
breast disease (1 paper, 2022). "Obese women without breast disease had the highest value, likely related to visceral fat production of resistin." (PMID 35627631, 2022). "In this regard, we observed that women with BMI > 25 kg/m2 within the BC group showed differences in the biochemical behavior of leptin, adiponectin, resistin, and adipsin levels compared to women without breast disease." (PMID 35627631, 2022).
cataract (1 paper, 2023). Partial or complete opacity of the crystalline lens of one or both eyes that decreases visual acuity and eventually results in blindness. "A higher level of omentin-1 and lower level of resistin were also shown in this study, in the entire group of cataract patients." (PMID 37892980, 2023). "The IL-6 and resistin concentrations, in turn, showed higher levels in all controls, i.e., by 30% (p < 0.05) and 64.9% (p < 0.001), respectively, compared to the cataract patients." (PMID 37892980, 2023). "The available literature lacks publications comparing serum concentrations of adiponectin, omentin-1 and resistin in cataract patients and healthy subjects." (PMID 37892980, 2023). "After dividing the groups by gender, the AcP and omentin-1 concentrations were higher and resistin concentrations were lower in female cataract patients, versus healthy female controls." (PMID 37892980, 2023). "Statistically significant differences were also found between cataract and healthy males for the measurements of IL-6, resistin and adiponectin concentrations—the IL-6 and resistin concentrations were lower, and the adiponectin levels were higher in the group of cataract patients." (PMID 37892980, 2023). "Likewise, the IL-6 and resistin concentrations were lower, while the concentrations of omentin-1 and adiponectin were higher, in females with cataract, relative to the levels measured in male controls." (PMID 37892980, 2023).
chronic bronchitis (1 paper, 2022). A type of chronic obstructive pulmonary disease characterized by chronic inflammation in the bronchial tree that results in edema, mucus production, obstruction, and reduced airflow to and from the lung alveoli. "Adipsin, lipocalin-2, IL-6 and resistin were significantly higher in the group with chronic bronchitis." (PMID 36291711, 2022).
Chronic colitis (1 paper, 2020). A chronic inflammatory disease of the large intestine (colon, cecum and rectum). "In spite of its adipokine character, resistin in humans is actually produced majoritarily by immune cells and is augmented in chronic colitis." (PMID 33537270, 2020).
chronic GVHD (1 paper, 2016). "Adiponectin and resistin levels were altered in patients with acute and chronic GVHD compared to autologous controls and were associated with overall survival and relapse mortality in patients undergoing allogeneic HSCT." (PMID 27374827, 2016). "In conclusion, adiponectin and resistin were altered during the occurrence of acute and chronic GVHD and were associated with overall survival and relapse mortality in patients undergoing allogeneic HSCT compared to autologous controls." (PMID 27374827, 2016).
coagulopathy (1 paper, 2025). "Consistent with the existing literature, an impaired cytokine profile (including IL8, NGAL, resistin, IL2R, and calprotectin) was observed, potentially contributing to erythrocyte damage, eryptosis, and coagulopathy." (PMID 41516267, 2025).
colitis (1 paper, 2011). Inflammation of the colon. "We observed similar resistin expression in adipose tissue, but resistin serum concentrations were higher in the colitis group compared to the other groups." (PMID 22073943, 2011).
colorectal tumor (1 paper, 2016). "The summary WMD of resistin levels between CRC patients and control group was 1.47 ng/mL (95% CI: 0.78 to 2.16), and z-score for overall effect was 4.19 (p < 0.0001), which revealed a possibility that higher circulating resistin level was associated with higher risk of colorectal tumor." (PMID 27642602, 2016).
copper metabolism disorders (1 paper, 2020). "Further studies, also involving in vitro studies to the effect of the polymorphism on RETN expression and resistin functionality, are needed to validate the role in copper metabolism disorders." (PMID 33142854, 2020).
dependence (1 paper, 2025). "RETN, the gene encoding resistin, has been shown to be involved in alcohol craving or dependence in humans." (PMID 41239854, 2025).
developmental delay (1 paper, 2019). "Third, we found that the group with regression plus developmental delay prior to the onset of ASD (16.5% of the sample) was significantly different from the rest of the sample as far as the higher plasmatic levels of resistin and PAI-1." (PMID 31835709, 2019).
dilatation (1 paper, 2022). "All markers were associated with inflammation and the first two (i.e., PTX3 and resistin), in particular, were independent of cervical dilatation." (PMID 35536791, 2022).
Dyskinesia (1 paper, 2023). A movement disorder which consists of effects including diminished voluntary movements and the presence of involuntary movements. "The level of leptin was increased both in ES (p < 0.001) and AS (p < 0.001) versus CG, while resistin was increased only in patients with dyskinesia (p < 0.05)." (PMID 37233709, 2023). "Moreover, resistin concentrations were statistically significant increased, whereas leptin level was decreased in the dyskinesia PD patients versus the control group." (PMID 37233709, 2023). "Thus, resistin might be a target in the prevention treatment against the development of dyskinesia in PD patients." (PMID 37233709, 2023). "Interestingly, resistin concentrations were elevated only in the PD dyskinesia patients, which indicates the potential role of this adipokine in the progression of PD leading to dyskinesia." (PMID 37233709, 2023). "For resistin and melatonin, lower concentrations were observed in patients without dyskinesia than those with dyskinesia." (PMID 37233709, 2023). "In the study group without dyskinesia, the resistin level was lower compared to the study group with dyskinesia." (PMID 37233709, 2023). "Melatonin, leptin, adiponectin, and resistin concentrations were measured in the blood serum of 20 PD patients without dyskinesia (ES), 24 PD patients with dyskinesia (AS), and 20 healthy volunteers as a control group (CG)." (PMID 37233709, 2023).
eating disorder (1 paper, 2020). A broad group of psychological disorders with abnormal eating behaviors leading to physiological effects from overeating or insufficient food intake. "Literature data suggested the effect of chronic energy restriction and eating disorders on resistin levels." (PMID 32560148, 2020).
endometrial tumors (1 paper, 2024). "Thus, endometrial tumors may utilize autocrine resistin signaling to promote metastasis." (PMID 38467625, 2024).
fetal macrosomia (1 paper, 2020). "This supports the notion that resistin has a direct effect on regulation of fetal development and may be related to the occurrence of fetal macrosomia." (PMID 33321877, 2020).